ZC2HC1A (zinc finger C2HC-type containing 1A)
Synonyms: C8orf70; FAM164A; CGI-62
Tractability: PROTAC: its protein half-life has been measured.
Gene: Protein-coding gene on chromosome 8 (78,666,050 to 78,719,765, forward strand). Ensembl gene ENSG00000104427.
Subcellular location (Human Protein Atlas): Cytosol; Actin filaments
Gene Ontology:
Molecular function: protein binding
Genetic constraint (gnomAD): Loss-of-function variants: 18 observed, 24.38 expected, observed/expected ratio (o/e) 0.74, 90% interval 0.51 to 1.1. The upper end of that interval is the gene's LOEUF score, 1.1, which puts it in group 4 of 6, group 1 being the genes least tolerant of losing a copy. Missense variants: 342 observed, 310.99 expected, observed/expected ratio (o/e) 1.1, 90% interval 1.01 to 1.2. Synonymous variants: 108 observed, 102.77 expected, observed/expected ratio (o/e) 1.05, 90% interval 0.9 to 1.23.
Homologues: Orthologues: chimpanzee ZC2HC1A (99% identical), macaque ZC2HC1A (98% identical), guinea pig ZC2HC1A (93% identical), dog ZC2HC1A (92% identical), pig ZC2HC1A (92% identical), rabbit ZC2HC1A (92% identical), mouse Zc2hc1a (87% identical), rat Zc2hc1a (86% identical), tropical clawed frog zc2hc1a (66% identical), zebrafish zc2hc1a (59% identical). Paralogues in human: ZC2HC1B (31% identical), ZNF474 (13% identical), ZNF475 (6% identical).
Diseases named in the same sentence as ZC2HC1A in open-access papers:
ZC2HC1A is named in the same sentence as 4 diseases in open-access papers, as found by Europe PMC text mining. Sharing a sentence is not in itself a finding about the gene and the disease. The quoted sentences say what the papers report.
cancer (1 paper, 2019). A tumor composed of atypical neoplastic, often pleomorphic cells that invade other tissues. "However, to date, very little is known about ZC2HC1A and PTGS1 and their roles in cancer." (PMID 31215439, 2019).
ZC2HC1A also shares sentences with these, for which no sentence is quoted: hepatocellular carcinoma (1 paper); retinal ciliopathy (1); retinal degeneration (1).